NGF (nerve growth factor)
Diseases named in the same sentence as NGF in open-access papers (continued):
Sharing a sentence is not in itself a finding about the gene and the disease.
leprosy (continued). "The authors theorized that the high level of the antibody in leprosy patients could explain the decrease in NGF." (PMID 41156731, 2025). "In this research, the ROC of the NGF curve could detect early disability of MB leprosy patients with a cut-off of 81.43 pg/mL." (PMID 33425178, 2020). "This research is the first conducted to determine the threshold of serum NGF in leprosy patients." (PMID 33425178, 2020). "ROC curve analysis of NGF: according to the ROC curve, the optimal cut-off value of serum NGF concentrations as an indicator for early disability in leprosy was 81.43 ng/L, with a sensitivity of 100% and a specificity of 100% [AUC 0.719; 95% CI (0.719-0.918); p < 0.05]." (PMID 33425178, 2020). "Further studies are needed to elucidate the broad role of NGF in the pathogenesis of leprosy." (PMID 29867937, 2018). "Finally, we highlight avenues of investigation for future research to broaden our understanding of the role of NGF in the pathogenesis of leprosy." (PMID 29867937, 2018). "From a clinical standpoint all these NGF system alterations found in leprosy skin correlated with the characteristic sensory deficit and the loss of skin neurotrophism that might lead to trophic ulcers and mutilation." (PMID 23190582, 2012). "A decrease in NGF has been also reported in leprosy-affected human skin and nerve." (PMID 23190582, 2012). "The NGF produced by keratinocytes has been found decreased in skin biopsies from leprosy patients." (PMID 23190582, 2012). "Understanding the regulation of NGF levels in different conditions of the disease and working on anti-NGF levels may be relevant for immunomodulatory treatment and for controlling neuroimmune reactions in leprosy." (PMID 41156731, 2025). "Therefore, this study utilized NGF as a marker for early deformities in leprosy." (PMID 33425178, 2020). "A cross-sectional study evaluated NGF tissue expression using immunohistochemistry in 47 HIV/leprosy co-infected patients and 61 leprosy-only patients." (PMID 41156731, 2025). "Data showed that the expression of NGF and NFGR increased more robustly in patients with TT leprosy than in HD." (PMID 36389696, 2022). "In contrast, the expressions of NGF and NGFR were negatively correlated with the proportion of dermal IL-17A–producing γδ T cells, indicating negatively regulation of IL-17A+ γδ T cells on NGF and NGFR expression in lesion of TT leprosy." (PMID 36389696, 2022). "Strong positive correlations exist between the levels of NGF, NGF-R, and TGF-β in patients with leprosy." (PMID 33425178, 2020). "There are strong positive correlations among the levels of NGF, NGF-R, and TGF-β in patients with leprosy." (PMID 29867937, 2018). "The characteristic positive correlations among NGF, NGF-R, and TGF-β in the clinical forms of leprosy highlight the interdependence of these factors." (PMID 29867937, 2018). "This study aimed to quantify the expression of NGF in skin lesions of patients with leprosy, with and without HIV co-infection, and to establish relationships with the different variables that characterize the nerve damage caused by the disease." (PMID 41156731, 2025). "Overall, co-infection with HIV did not influence the increase in NGF in the lesions of leprosy patients compared with patients with leprosy alone." (PMID 41156731, 2025). "Evaluate the expression of IL-17, NGF and NGRF in the different clinical forms of leprosy." (PMID 39308868, 2024). "In addition, we determined the levels of NGF and NGFR in leprosy lesion using real-time polymerase chain reaction (PCR)." (PMID 36389696, 2022). "Moreover, a significant loss of intra-epidermal innervation, and a lowered expression of sensory neuromodulators that are under NGF control, such as Substance P and the sodium channel SNS/PN3, have been found in leprosy-affected skin." (PMID 23190582, 2012).
leprosy (continued). "The main objective of this study was to analyze the expression of NGF in leprosy lesions and observe possible differences between patients coinfected with HIV, thus assuming that the presence of HIV could increase neural damage, affecting the expression of NGF." (PMID 41156731, 2025).
liver fibrosis (7 papers, 2014 to 2023). "In order to better understand the role of NGF produced by stress stimulus on liver fibrosis, we evaluated the expression of the receptors involved in NGF responses, tropomyosin-receptor-kinase A (TrkA), and p75 neurotrophin receptor (p75NTR)." (PMID 34064584, 2021). "In the first stage of liver fibrosis and inflammation (F1/A1), NGF mRNA levels were significantly higher than in other liver injury stages, and p75NTR mRNA levels were lower." (PMID 25816145, 2015). "The most highly represented gene families in the grouping of hepatic fibrosis were the collagens (Col, n = 10) while in the category of axonal guidance were members of different gene families including NGF, PlexinB1, EphrinB3, Semaphorin6C, and L1CAM." (PMID 26156969, 2015). "In cases of liver cirrhosis, higher p75NTR mRNA expression was observed, whereas NGF was expressed at higher levels in patients with hepatic fibrosis." (PMID 25816145, 2015). "Another well-studied effect of NGF is to induce apoptosis of hepatic stellate cells and consequently resolve liver fibrosis." (PMID 25397406, 2014). "In liver, NGF has been demonstrated to play a role in regulating liver fibrosis, carcinogenesis, angiogenesis, and cholangiocyte proliferation." (PMID 25397406, 2014). "It has been proved that NGF can improve liver fibrosis by regulating HSC cell apoptosis." (PMID 37405258, 2023). "Here, in a murine model of TAA-induced liver fibrosis we identified nerve growth factor (NGF) to be a crucial regulator of the stress-induced fibrogenesis signaling pathway as it activates its receptor p75 neurotrophin receptor (p75NTR), increasing liver damage." (PMID 34064584, 2021). "Additionally, blocking the NGF decreased liver fibrosis whereas treatment with recombinant NGF accelerated the fibrotic process to a similar extent than stress challenge." (PMID 34064584, 2021). "We observed that stress increased liver fibrosis by the upregulation of NGF." (PMID 34064584, 2021). "Several reports have partially demonstrated that stress contributes to the fibrosis induction and/or liver injury, however, this is the first report to identify the NGF as a critical mediator responsible for the deleterious effect of stress observed during experimental liver fibrosis." (PMID 34064584, 2021). "In parallel, the plasma NGF levels also increased along with the progression of liver fibrosis." (PMID 25397406, 2014). "After observing that NGF is upregulated in the liver of mice after TAA and stress challenge, we decided to neutralize it and evaluate the effect on liver fibrosis." (PMID 34064584, 2021). "It will be interesting to follow how NGF, proNGF, monoclonal antibodies against NGF, non-peptidic NGF agonists and other drug systems that target the NGF route will modulate experimental hepatic fibrosis." (PMID 26779021, 2015).
lung carcinoma (7 papers, 2008 to 2024). "Leptomeningeal reaction was associated with up regulation of signaling pathways also important in pancreatic and lung cancers, while being associated with down regulation of NGF and UVB-induced MAPK signaling." (PMID 28781988, 2017). "To further investigate this, we created a neuroinvasive in situ lung cancer model by injecting NGF into mice with seeded tumors." (PMID 39385213, 2024). "NGF and its receptors are expressed in lung cancer, and this autocrine stimulus plays an important role in the development of malignant tumors and is associated with low tumor survival rates." (PMID 35359739, 2022). "Previous studies have shown that the expression of TrkA and NGF is high in NSCLC, but the disposition of TrkA and NGF in various subtypes of lung cancer is still unclear." (PMID 34502019, 2021). "Although early studies have shown that NGF is expressed in lung cancer, few data on its clinicopathological significance are available." (PMID 34502019, 2021). "Overall, this study highlights the overexpression of NGF, proNGF and their receptors TrkA, p75NTR in lung cancer with a differential expression related to histological subtypes." (PMID 29802376, 2018). "Based on the present findings, the biological effect of targeting TrkA and NGF in lung cancer should be revisited in the context of squamous cell carcinomas with more functional in vitro and in vivo animal models." (PMID 29802376, 2018). "The present study aimed to clarify the expression and clinicopathological significance of TrkA, NGF, proNGF, p75NTR and sortilin in lung cancer." (PMID 29802376, 2018). "To address this, we undertook a simultaneous investigation of the protein expression of proNGF, NGF, TrkA, p75NTR and sortilin in the same cohort of lung cancers and normal lung tissues." (PMID 29802376, 2018). "Our results reveal that TrkA, NGF, proNGF, p75NTR and sortilin are differently expressed across lung cancer histological subtypes, with TrkA and NGF most particularly increased in squamous cell carcinomas." (PMID 29802376, 2018). "We report an increased level of TrkA and NGF in squamous cell carcinomas, suggesting that drugs targeting the NGF-TrkA pathway in lung cancer should be used preferentially in this form of the disease." (PMID 29802376, 2018). "Therefore, our study provides a refinement in terms of quantification of TrkA and NGF in lung cancer subtypes, highlighting a significant increase in both TrkA and NGF expression in squamous cell lung cancer." (PMID 29802376, 2018). "In lung cancer, drugs targeting TrkA are in clinical trials, but the clinicopathological significance of TrkA and NGF, as well as that of the precursor proNGF, the neurotrophin co-receptor p75NTR and the proneurotrophin co-receptor sortilin, remains unclear." (PMID 29802376, 2018). "A previous study has shown that the expression of TrkA and NGF is higher in NSCLC8, but the distribution of TrkA and NGF in the different subtypes of lung cancer remains unclear." (PMID 29802376, 2018). "Similar autocrine stimulation of cancer cell growth via a proNGF/NGF autocrine loop involving TrkA has been described in breast cancer and may also apply to lung cancer." (PMID 29802376, 2018). "We also measured NGF levels in the tumor lysate of the mouse lung cancer model." (PMID 19517020, 2009). "Additionally, it was found that the levels of TrkA and NGF in squamous cell carcinoma were upregulated, indicating that lung cancer drugs that target the NGF–TrkA pathway could be used for this disease." (PMID 34502019, 2021). "Although the pathology of each lung disease may be different, in diverse microenvironments, NGF participates in the occurrence and development of lung diseases, like PF, bronchial asthma, and lung cancer, through changing protein expression levels and mediating cell function." (PMID 34502019, 2021).
lung carcinoma (continued). "Our study showing that there is no expression of the receptors TrkA, p75NTR and sortilin in nerves infiltrated in the tumor microenvironment, suggest that NGF/proNGF are not involved in stimulating the growth of nerves in lung cancer." (PMID 29802376, 2018). "ProNGF and sortilin have not been described in lung cancers and there has been limited reports on the expression of NGF and its receptors TrkA and p75NTR8,10,11." (PMID 29802376, 2018).
mental disorder (7 papers, 2017 to 2025). A disease that has its basis in the disruption of mental process. "A recent study reported an association between functional impairment and serum NGF levels in mental disorders." (PMID 31105606, 2019). "BDNF and NGF both are essential proteins for neuron's growth, and their dysregulation is seen in various mental disorders." (PMID 38376038, 2024). "In contrast, dysregulation of growth factors in the CNS has been associated with comorbid mental disorders, particularly BDNF and NGF." (PMID 29108028, 2017).
Myalgia (7 papers, 2010 to 2023). "So far, it is suspected that systemic administration of TrkB agonists can lead to anorexia and weight loss, and systemic therapy with nerve growth factor (NGF) has been shown to evoke myalgias and arthralgias." (PMID 21261959, 2011). "This association may propose NGF as a possible marker for studying psychological dysfunction in TMD myalgia." (PMID 32842964, 2020). "Patients with TMD-myalgia further had lower levels of salivary NGF and BDNF, but higher plasma BDNF." (PMID 32842964, 2020). "The production of recombinant human NGF (rhNGF) has been first developed and tested in phase I clinical trial, where moderate side effects, such as myalgias and injection site hyperalgesia, were evidenced in healthy subjects." (PMID 23190582, 2012). "A possible explanation for the decreased levels of NGF in TMD-myalgia may be related to the psychological characteristics of these patients." (PMID 32842964, 2020). "Contrary, in the current study we found significantly lower levels of salivary NGF in TMD-myalgia." (PMID 32842964, 2020). "Further studies are however needed to elucidate the mechanisms for NGF in TMD-myalgia." (PMID 32842964, 2020). "Based on previous studies of conditions associated with chronic pain, elevated levels of NGF might be expected in TMD-myalgia." (PMID 32842964, 2020). "In a similar manner, the RCT investigating recombinant human NGF demonstrated a high degree of unblinding related to injection site myalgia, which when accounted for in a separate analysis reported a more attenuated treatment-related difference which consequently lost statistical significance." (PMID 21203440, 2010). "The first one reported a decrease in NGF and BDNF in the saliva and only an increase in plasma BDNF in patients with TMD-myalgia." (PMID 37569811, 2023). "The current study showed that experimental myalgia induced by NGF and glutamate can increase the density of masseter sensory afferent nerve fibers as well as the expression of NR2B and NGF." (PMID 34341446, 2021). "The main aim of this study was therefore to compare the concentration of glutamate, 5-HT, NGF, BDNF, and SP in saliva and plasma from a well-defined group of TMD-myalgia patients with a matched healthy pain free control group." (PMID 32842964, 2020). "The main findings were significantly different levels of salivary glutamate, NGF, and BDNF in patients with a diagnosis of TMD-myalgia compared to pain-free healthy controls." (PMID 32842964, 2020). "Since decreased NGF has been associated with psychological impairment, our findings indicate that the decreased NGF levels in the study group may reflect comorbid psychological maladjustment usually associated with TMD myalgia and may not be related to the pain itself." (PMID 32842964, 2020). "The concentrations of NGF and BDNF, together with glutamate, serotonin, and SP, in saliva and plasma from a well-defined group of patients with chronic TMD-myalgia (n = 39) and in a group of pain-free controls (n = 39) in a clinical examination have been evaluated." (PMID 37569811, 2023). "In particular, the ocular NGF seems not to give rise to systemic effects on the perception of pain (myalgias, hyperalgesia) reported in clinical trials with systemic or intra-cerebroventricular administration." (PMID 23190582, 2012).
Sensory neuropathy (7 papers, 2016 to 2024). Peripheral neuropathy affecting the sensory nerves. "There have been extensive studies regarding peripheral sensitisation by varying inflammatory mediators in response to injury, including the role of NGF–TrkA signalling in the pathophysiology of peripheral sensory neuropathy." (PMID 39428813, 2024). "A previous study found a protective effect of NGF gene therapy against pyridoxine induced sensory neuropathy in a dog model." (PMID 26728069, 2016).
Sjögren’s syndrome (7 papers, 2010 to 2025). "Our research provides a list of novel targets and supports the involvement of an NGF-mediating proteolytic deregulation pathway as a focus point towards the better understanding of the underlying mechanism of Sjögren’s syndrome." (PMID 34305928, 2021). "Such elevated NGF levels have been previously reported in inflammatory diseases such as Sjögren syndrome." (PMID 25418464, 2014). "We also confirmed the correlation between serum NGF concentrations and gammaglobulins levels, as previously demonstrated in primary Sjögren's syndrome." (PMID 21085492, 2010). "Indeed, serum NGF concentrations are increased in juvenile arthritis, Kawasaki disease, Behçet’s disease, systemic sclerosis and primary Sjögren’s syndrome." (PMID 24223945, 2013). "A human recombinant NGF (Cenergermin) has been FDA-approved for neurotrophic keratitis and it is currently under clinical trial for severe Sjögren-Syndrome DED." (PMID 36091713, 2022). "Increased NGF and BDNF plasmatic levels have also been recently reported in primary Sjögren's syndrome in correlation with systemic activity and B and T cell activation." (PMID 21085492, 2010).